INS (insulin)
Diseases named in the same sentence as INS in open-access papers (continued):
Sharing a sentence is not in itself a finding about the gene and the disease.
Insulin resistance (continued). "The analysis indicated that insulin resistance outcomes for interventions B versus N, as well as insulin outcomes for interventions B versus N, demonstrated poor consistency (p < 0.05)." (PMID 41346675, 2025). "Visceral fat also releases pro-inflammatory molecules like TNF-α and IL-6, which interfere with insulin signaling and worsen insulin resistance." (PMID 40612313, 2025). "Excess cortisol contributes to insulin resistance by interfering with normal insulin signaling, hindering cellular glucose uptake." (PMID 40508878, 2025). "Some of the mechanisms contributing to this effect were the reduction of liver enzymes involved in glucose metabolism, the increase in insulin levels, and the reduction of insulin resistance." (PMID 39796209, 2025). "Insulin and cortisol as well as insulin resistance were all found significantly elevated in SZ patients." (PMID 40141202, 2025). "In DM patients, chronic hyperglycemia through IL-1β secretion from various cell types, including β cells, triggers a strong danger signal that impairs insulin secretion, promotes β-cell death, and contributes to insulin resistance." (PMID 40507468, 2025). "People with T2DM and prediabetes exhibit various degrees of insulin resistance —a condition involving elevated blood sugar levels and the body’s compensatory response of increased insulin production." (PMID 40283451, 2025). "It is assumed that increased basal GLP-1 levels enlarge the pancreatic β-cell reservoir to compensate the greater need of insulin due to insulin resistance and to counteract weight gain." (PMID 40271225, 2025). "The cross‐sectional design does not allow for dissecting the direction of the reciprocal influence between hepatic insulin resistance, impaired insulin clearance, and OSA." (PMID 40365648, 2025). "Insulin resistance is characterized by a defect in insulin-stimulated glucose uptake in adipose and other tissues and leads to hyperinsulinemia." (PMID 40863113, 2025). "This phenomenon, referred to as insulin resistance, features elevated glucose and insulin levels in the bloodstream." (PMID 39995417, 2025). "Obesity is a significant factor in the development of DM, as it increases substances that lead to insulin resistance and interfere with insulin signaling pathways." (PMID 40995591, 2025). "Fasting blood glucose and insulin were used to validate the insulin resistance in patients with MetS." (PMID 40303518, 2025). "In terms of glucose metabolism phenotypes, compared with those in the BCN-F group, fasting serum glucose (p < 0.01) levels, fasting serum insulin (p < 0.001) levels, and homeostasis model assessment — insulin resistance (HOMA-IR, p < 0.001) levels increased." (PMID 40097405, 2025). "Preclinical studies indicate that CBD improves insulin sensitivity in both in vitro and in vivo models, primarily by reducing inflammation, which plays a key role in insulin resistance." (PMID 40283884, 2025). "Given the liver’s central role in glucose and lipid metabolism, ER stress in this organ can impair insulin signaling pathways and contribute to hepatic insulin resistance, a key feature in the pathogenesis of T2D." (PMID 40964166, 2025). "Elevated ROS levels not only damage β-cells but also activate stress kinases that interfere with insulin signaling, aggravating insulin resistance." (PMID 40260393, 2025). "The meta-analysis found significantly higher circulating fasting insulin and C-peptide levels, as well as higher Homeostasis Model Assessment of Insulin Resistance (HOMA-IR) values, in adolescents with obesity compared with those without obesity." (PMID 40218969, 2025). "Endothelial dysfunction-induced reductions in insulin signaling lead to insulin resistance, linking the metabolic and cardiovascular components of metabolic syndrome." (PMID 40149950, 2025).
Insulin resistance (continued). "IR, assessable through homeostatic model assessment for insulin resistance, insulin sensitivity index, and quantitative insulin sensitivity check index, has been identified to be a risk factor for NAFLD in PCOS." (PMID 40087649, 2025). "BMEE lowered FBG levels, increased oral glucose tolerance, increased insulin sensitization, and reduced insulin resistance." (PMID 39803222, 2025). "The upregulated miRNAs in the HBER IST-Cell line were related to endocrine resistance, insulin resistance and the insulin signaling pathway." (PMID 40549708, 2025). "Insulin and adipose tissue further influence immune homeostasis; insulin resistance fosters a pro-inflammatory milieu characterized by M1 macrophage infiltration into visceral fat depots, elevated IL-1β, and reduced adiponectin." (PMID 40729034, 2025). "Pharmacological treatments address hormonal and metabolic derangements: metformin remains a cornerstone for insulin resistance and hyperinsulinemia, both improving ovulation and indirectly reducing insulin-induced ROS production." (PMID 40694958, 2025). "In this regard, our modified HFD/STZ-induced DbCM model exhibits T2DM, reflected by hyperglycaemia, insulin resistance, and reduced insulin sensitivity, in parallel with progressive LV diastolic dysfunction with preserved ejection fraction and blood pressure." (PMID 40814000, 2025). "The main characteristics of T2D are insulin resistance and impaired insulin secretion, leading to hyperglycemia, whereas CVDs are linked with chronic inflammation and oxidative stress, leading to atherosclerosis." (PMID 40332079, 2025). "The results demonstrated that cycling, resistance training, and combined resistance and aerobic training effectively improved fasting blood glucose levels, insulin levels, and insulin resistance." (PMID 40951419, 2025). "Investigations should aim to dissect how insulin modulates anabolic and catabolic pathways in various tissues, providing insights for managing insulin resistance and metabolic diseases." (PMID 40725728, 2025). "Females with better diet/lifestyle scores had lower fasting insulin and insulin resistance (HOMA-IR)." (PMID 41431696, 2025). "Male rats had a higher plasma insulin concentration and insulin resistance index compared to females." (PMID 39821966, 2025). "Obesity is strongly associated with insulin resistance and an increased risk of type 2 diabetes, the ARC-treated HFD mice showed improved insulin sensitivity and better tolerance to a glucose load." (PMID 40369420, 2025). "This normalization of fasting insulin occurred independently of any changes of insulin resistance, fasting glucose, and fasting free fatty acids." (PMID 41009753, 2025). "Insulin resistance is characterized by a diminished response of target tissues to insulin, leading to impaired glucose homeostasis and subsequent metabolic derangements." (PMID 40002771, 2025). "These cytokines directly damage pancreatic β-cells, impair insulin secretion, and induce insulin resistance, thereby accelerating the onset and progression of T2DM." (PMID 40559421, 2025). "miRNAs are major players in the pathogenesis of T2DM, starting with pancreatic development, insulin secretion, and insulin resistance." (PMID 40533788, 2025). "Regular consumption of high-glycemic foods and refined sugars can spike insulin levels, leading to insulin resistance over time." (PMID 40519768, 2025). "PTEN negatively regulate brain insulin sensitivity leading to the development of brain insulin resistance." (PMID 40251348, 2025). "Insulin resistance is characterized by a reduced response of the body to the metabolic actions of insulin, which is essential for carbohydrate and lipid metabolism." (PMID 39756373, 2025). "Ceramides impair insulin signaling in a species- and tissue-specific manner; in skeletal muscle, CerS1-derived C18:0 ceramides promote insulin resistance and are required for full glucose intolerance." (PMID 41002965, 2025).
Insulin resistance (continued). "In these participants, high levels of plasma glucose and insulin exhibited 106% and 57% respective increased prevalence of insulin resistance compared with their counterparts with normal levels of the parameters." (PMID 40273152, 2025). "Impaired activation of the insulin pathway leads to reduced tissue-specific insulin action and ultimately systemic insulin resistance as mice age." (PMID 40747301, 2025). "Feeding mice with a diet containing 60% fat resulted in a significant increase in body weight, elevated serum levels of TG, CHOL, and INS, and decreased glucose tolerance and insulin resistance." (PMID 41278194, 2025). "In the context of insulin resistance, the clearance of damaged mitochondria in insulin-sensitive cells relies on mitophagy." (PMID 39966707, 2025). "Type 2 diabetes mellitus (T2DM) is a chronic metabolic condition marked by either insulin resistance or insufficient insulin secretion, contributing to rapidly elevated blood glucose levels." (PMID 40568559, 2025). "In a mouse model, one study showed that uric acid can also influence insulin signaling directly, which can lead to insulin resistance." (PMID 41019334, 2025). "An animal study demonstrated that melatonin treatment significantly improved hyperglycemia in T2DM rat models by reducing insulin levels, inhibiting hemoglobin glycation, and ameliorating insulin resistance." (PMID 40698248, 2025). "The relative levels of these adipokines are such that they adversely affect insulin sensitivity; adiponectin improves insulin signaling, while resistin blocks it, thus leading to insulin resistance and facilitating the progression from MASLD to T2DM." (PMID 41220583, 2025). "This disruption in insulin signaling contributes to insulin resistance, a key factor in the development of T2DM." (PMID 40362254, 2025). "These inflammatory cytokines interfere with insulin signaling pathways, leading to insulin resistance, a critical factor in the development of obesity and type 2 diabetes." (PMID 40481056, 2025). "Insulin resistance in VSMCs disrupts normal insulin signaling pathways, particularly those involving insulin receptor substrate-1 (IRS-1) and downstream PI3K-Akt signaling." (PMID 40564010, 2025). "The exercise condition decreased insulin area under the curve (25 ± 22%), increased estimated insulin (35 ± 62%) and decreased insulin resistance (9 ± 35%; p < 0.05), compared with control (p > 0.05)." (PMID 39654298, 2025). "First, this study provides data on insulin physiology (insulin resistance/sensitivity, β-cell function) of GDM subtypes, and we evaluated the associations with multiple core pregnancy outcomes that were rigorously recorded." (PMID 39446494, 2025). "Perturbations in glucose metabolism due to insulin resistance are exacerbated when insulin production is compromised, as seen in patients with T2DM." (PMID 40689212, 2025). "M1 macrophages produce proinflammatory cytokines like TNF-α, IL-6, and monocyte chemoattractant protein (MCP-1), which reduce insulin signaling in different tissues, thus contributing to insulin resistance and the onset of T2D." (PMID 40362446, 2025). "In general, T2D has been associated with excessive nutritional intake that results in elevated insulin secretion, insulin resistance, and obesity." (PMID 40074175, 2025). "Insulin resistance, defined as a diminished biological response of key target tissues, such as liver, muscle, and adipose tissue to normal or elevated circulating insulin levels, plays a central role in the development of obesity-related metabolic diseases." (PMID 40699742, 2025). "Participants with higher TFC frequencies generally had lower HDL, total cholesterol, fasting glucose, and smoking rates, but higher income, weight, height, insulin, and insulin resistance." (PMID 41383580, 2025). "The etiology of insulin resistance consists of different determinants that can control complex and multidimensional insulin signaling." (PMID 40311678, 2025).
Insulin resistance (continued). "Insulin resistance (IR) refers to the body’s weakened response to insulin signals, resulting in the inability of insulin to effectively promote glucose uptake and utilization, resulting in high blood glucose and increased insulin secretion." (PMID 40417223, 2025). "TNF-α is known to interfere with insulin signaling, which leads to insulin resistance, a core feature in PCOS." (PMID 40385768, 2025). "Previous animal studies have simulated insulin resistance by activating insulin signaling pathways through acute insulin treatment of primary embryonic cortical neurons." (PMID 40474525, 2025). "IGF1R which is a tyrosine kinase, plays a vital role in insulin signaling leading to insulin resistance." (PMID 40533788, 2025). "Glutamine facilitates the release of glucagon-like peptide-1 and boosts insulin secretion, whereas glutamate can elevate glucagon secretion and worsen insulin resistance." (PMID 41458553, 2025). "Type 2 diabetes is the most common form, initially characterized by insulin resistance with compensatory hyperinsulinemia, followed by progressive β-cell dysfunction that leads to insufficient insulin secretion over time." (PMID 41159201, 2025). "Two commonly used insulin-based indices for IR are the Homeostatic Model Assessment of Insulin Resistance (HOMA-IR) and the Quantitative Insulin Sensitivity Check Index (QUICKI)." (PMID 40778272, 2025). "As TyG has been validated in the literature against the hyperinsulinemic–euglycemic clamp as a marker of insulin resistance, its reduction reinforces the improvement in the glucose–insulin axis with the AKMP and complements the interpretation of HOMA-IR." (PMID 41305609, 2025). "In insulin resistance, pancreatic β-cells attempt to overcome the diminished effects of insulin by producing more of the hormone." (PMID 40076851, 2025). "miR-122 controls both the insulin signaling pathway and glucose metabolism in hepatic insulin resistance." (PMID 40565979, 2025). "T2DM, on the other hand, is characterised by insulin resistance in the target tissue, relatively insufficient insulin secretion and resulting dysfunction of the β-cells, which often causes no symptoms." (PMID 40894207, 2025). "Obesity, in turn, causes low-grade Th1-type systemic inflammation, characterized by increased production of cytokines, which, directly or indirectly, block the action of insulin, worsening peripheral insulin resistance." (PMID 38778593, 2025). "Advanced insulin resistance triggers pancreatic β-cell dysfunction, leading to reduced insulin secretion and consequently decreased insulin-mediated uric acid reabsorption." (PMID 41179564, 2025). "OGT deletion also reduces circulating insulin levels and improves insulin resistance, glucose tolerance and insulin sensitivity; the liver is also improved by OGT deletion, as indicated by reduced lipid content." (PMID 41000247, 2025). "In patients with T2DM, persistent hyperglycemia due to insulin resistance and insufficient insulin secretion can lead to metabolic acidosis." (PMID 39866566, 2025). "Smoking tobacco negatively affects metabolic syndrome by reducing insulin sensitivity and increasing insulin resistance as well as increasing the amount of cortisol and catecholamine, which are known to have insulin-antagonistic properties." (PMID 40519247, 2025). "Previous studies have demonstrated that higher serum IGFBP-rp1 is involved in the early defect of insulin actions; therefore, it serves as a marker of insulin resistance, metabolic syndrome, T2DM, and related cardiovascular complications." (PMID 41226444, 2025). "Estrogen protects against insulin resistance by activating the ERα pathway in insulin-sensitive tissues." (PMID 40474901, 2025). "PTP1B impairs hypothalamic insulin and leptin signaling and is upregulated in obesity, where it contributes to central insulin resistance." (PMID 40699839, 2025).
Insulin resistance (continued). "This compensatory hyperinsulinemia can lead to insulin resistance where more insulin is required to maintain homeostasis in blood glucose levels." (PMID 39821966, 2025). "Hyperglycemia is frequently accompanied by insulin resistance, and elevated insulin levels stimulate sympathetic nerve excitation, simultaneously, high FBG levels damage endothelial cells, leading to vasoconstriction and elevated blood pressure." (PMID 40510470, 2025). "At a molecular level, insulin resistance is defined as an impaired cellular response to insulin, resulting in a decreased capacity for glucose disposal in response to the insulin signal." (PMID 40013621, 2025). "Insulin resistance (IR) is a pathological condition characterized by the diminished ability of cells to uptake glucose in response to insulin." (PMID 41567335, 2025). "The results of this study suggested that the increase in insulin sensitivity and the improvement in insulin resistance by CJE ameliorate lipid metabolism disruptions, which further inhibit the abnormal changes in lipid profile indices in T2DM mice." (PMID 40077469, 2025). "Based on UCP glucose and UCP insulin, we calculated the neonatal homeostatic model assessment of insulin resistance (HOMA‐IR; Hancox & Landhuis, 2011)." (PMID 40013652, 2025). "Clinical studies of antiandrogenic treatment has been shown to partially improve insulin resistance, highlighting the role of androgen excess on the impairment of insulin action." (PMID 40443457, 2025). "From a pathogenetic perspective, obesity contributes to insulin resistance by fostering metabolic inflammation and lipotoxicity which, in turn, are two pivotal mechanisms in impairing insulin signaling." (PMID 40263184, 2025). "In insulin resistance, the promotion of protein synthesis by insulin is impaired, whereas its promotion of protein catabolism is enhanced." (PMID 41048435, 2025). "In obesity and T2D, insulin resistance develops, marked by impaired insulin-stimulated glucose uptake and persistent hepatic gluconeogenesis." (PMID 40806697, 2025). "The cohort of 70 adolescents presented with hypertriglyceridemia (average steatosis score = 2.3) and insulin resistance (average HOMA-IR = 7.0 with HOMA-IR = glucose (mmol/L) x insulin (μIU/mL)/22.5)." (PMID 40425812, 2025). "This cycle directly impairs β-cell function and inhibits insulin secretion while simultaneously exacerbating insulin resistance in peripheral tissues by disrupting insulin signal transduction." (PMID 41301787, 2025). "A prospective cohort study involving 48 postmenopausal osteoporotic nondiabetic women showed that 1-month denosumab therapy decreased fasting insulin by 10.5 pmol/L and homeostatic model assessment of insulin resistance (HOMA-IR) by 0.5." (PMID 40149867, 2025). "The progression to requiring insulin therapy is determined by a complex interplay of factors beyond insulin resistance, including β-cell reserve and secretory capacity." (PMID 41225974, 2025). "Nonetheless, we demonstrate for the first time that circulating EVs from insulin-resistant individuals carry active phosphatases responsible for the insulin resistance induced by these EVs." (PMID 39422717, 2025). "Polycystic ovary syndrome (PCOS) is primarily characterized by insulin resistance, which leads to increased hepatic glucose production and impaired insulin-mediated glucose disposal." (PMID 40547527, 2025). "Insulin resistance—defined by reduced cellular responsiveness to insulin—leads to hyperglycemia, hyperinsulinemia, and dyslipidemia, all of which contribute to vascular injury." (PMID 40429748, 2025). "For instance, exosomes from the muscle and fat cells contain miR-1 and miR-133, which target IRS-1 and INSR, inhibiting insulin signaling and leading to insulin resistance." (PMID 41438998, 2025).